MMP2 (matrix metallopeptidase 2)
Diseases named in the same sentence as MMP2 in open-access papers (continued):
Sharing a sentence is not in itself a finding about the gene and the disease.
cancer (continued). "Genipin presents inhibitory effect on the MMP-2 activities, which is responsible for the invasiveness of cancer cells." (PMID 23029478, 2012). "MMP-2, a 72 kDa protein also called gelatinase A, is the most abundant of the MMPs and is documented as a marker of poor prognosis in a variety of cancers." (PMID 22745734, 2012). "There is a differential expression of MMP-2 in bone marrow micrometastasis, where the presence of MMP-2 detected by immunocytochemistry is in almost all cases zero in low grade cancer and suggests the inhibition of MMP-2." (PMID 23227342, 2012). "Firstly the stromal cells inhibit MMP-2 expression, then with cancer progression the cancer cells induce stromal expression of MMP-2, which in turn leads to the release of other growth factors and angiogenic factors." (PMID 23227342, 2012). "The functions of NF-κB in the transcription of the mesenchymal genes encoding VEGF, Vimentin, MMP-2 and MMP-9 are critical for promoting and maintaining a mesenchymal phenotype in cancers." (PMID 22640183, 2012). "In CRC, MMP-2 immunoexpression associates with advanced disease, and high MMP-2 expression in cancer cells and the stroma associates with poor prognosis." (PMID 23216739, 2012). "Both MMP-2 and 9, which are abundantly expressed in various malignant tumors, contribute to cancer invasion and metastasis." (PMID 24278749, 2012). "Several evidences suggest that MAPKs (JNK 1/2, ERK 1/2, and p38) play important roles in cancer cell migration, invasion, and MMP-2 activity." (PMID 23226337, 2012). "Upregulation of the matrix metalloproteinases MMP-2 and MMP-9 in various cancers has been associated with worse survival of the patients." (PMID 22472880, 2012). "Matrix metallo peptidases like MMP3 and MMP2 were slightly upregulated in normal and cancer cells respectively." (PMID 22321936, 2012). "Degradation of ColIV was closely related to increased MMP-2 and MMP-9 expression; MMP-9 have more important function than MMP-2 during the cancer development." (PMID 23107277, 2012). "As cancer cells adhere and invade, the mesothelium stimulates MMP2/9 to induce mesothelial cell apoptosis." (PMID 22888339, 2012). "MMP-2 and MMP-9 have been implicated following lung transplant remodelling and injury as well as having pathological roles in inflammation, cancer, and cardiovascular disease." (PMID 22593690, 2012). "Another study found MMP-2 to be more frequently expressed in benign tumors with morphological altered lesions than in established carcinomas." (PMID 22200690, 2012). "As expected, MMP expression in normal mucosa was lower than in carcinoma tissue: 2-fold lower for MMP-2 (median carcinomas 10.6 ng mg−1 protein) and 12-fold lower for MMP-9 (median carcinomas 36.7 ng mg−1 protein)." (PMID 22472880, 2012). "In the OTSCC tissues, MMP-2 expression was mainly observed in the stromal cells surrounding the epithelial nests of carcinoma (MMP-2: iOD 357.79 ± 116.78)." (PMID 23107277, 2012). "Increased levels of MMP-9 and MMP-2 expression have been correlated with an invasive phenotype of cancer cells." (PMID 21813027, 2011). "MMP-2 is one of the enzymes in degradation of basement membrane collagen and has a major role in cancer cell invasion." (PMID 21969874, 2011). "Among MMPs, MMP-2 and MMP-9 have mainly been associated with malignant tumor progression and metastasis in both human and canine tumors." (PMID 21726449, 2011). "This co-chaperone complex enhances Hsp90α-mediated activation of MMP-2 in vitro, while inhibition of Hsp70 in conditioned media reduces this activation and decreases cancer cell migration and invasion." (PMID 21533148, 2011). "Capacity of the major product of COX-2, the prostaglandin E2 (PGE2), to stimulate the production of the matrix metalloproteinase-2 (MMP-2) and cancer cell invasion were assessed with a zymography gel and invasion chambers." (PMID 21792195, 2011).
cancer (continued). "MT1-MMP expression generally correlates well with MMP-2 activation in various human cancers, suggesting that MT1-MMP plays an important role in cancer cell invasion." (PMID 21726449, 2011). "This radiation-enhancement of cancer cell invasion was associated with an increase in COX-2 and MMP-2 expression." (PMID 21792195, 2011). "MMP-2 has been shown to be important in development and cell motility, and has a well-documented role in cancer metastasis." (PMID 21533148, 2011). "Further supporting the potential role of COX-2, addition of PGE2 has increased cancer cell invasion and release of MMP-2 from the MDA-MB-231 cells." (PMID 21792195, 2011). "Among all the MMPs, MMP-2 and -9 have demonstrated to play a major role in the establishment of metastasis, which substantially increases in majority of malignant tumors." (PMID 21826183, 2011). "The inhibition of extracellular Hsp70 reduces MMP-2 activation and decreases cancer cell migration and invasion, implicating this co-chaperone as an additional extracellular therapeutic target." (PMID 21533148, 2011). "This prostaglandin can be involved in cancer cell invasion by stimulating the expression of matrix metalloproteinase 2 (MMP-2)." (PMID 21792195, 2011). "This complex matures after binding to αvβ3 integrin at the cancer cell surface, which concentrates the active MMP-2 at the migrating front." (PMID 21792195, 2011). "Regulatory mechanisms and inhibitors on MMP-2 protease activity have been extensively studied in cancer research." (PMID 21969874, 2011). "Up-regulations of gene expression and secretion of MMP-2 in both cancer cells and surrounding stromal cells have been shown to promote cancer progression and metastasis." (PMID 21969874, 2011). "Bands for the active form of MMP-2 were found in 94% of the carcinoma samples and 17% of the benign tumor samples." (PMID 21726449, 2011). "The percentage of fibroblasts that were positive for MMP-9 staining was lower than the percentage that were positive for MMP-2 in carcinomas." (PMID 21726449, 2011). "Expression of MMP-2, MMP-9 and TNF-α is strongly linked with malignant tumor progression, angiogenesis and metastasis of various types of cancers." (PMID 20573279, 2010). "Cancer cells capable of producing these enzymes, especially of gelatinases MMP-2 and -9, have been shown to have increased invasion potential in several malignancies." (PMID 20671952, 2010). "Previous studies have shown that one of the mechanisms underlying SDF-1-induced cancer cell invasion is activation of MMP-9 and MMP-2." (PMID 21167057, 2010). "The mean levels of serum TIMP-2 and MMP-2-TIMP-2 complex were higher in the healthy controls compared to those with a malignant tumor." (PMID 20671952, 2010). "Among the MMPs induced by CD147, malignant progression has been most closely correlated with the expression of MMP-2 in several forms of cancer, and the increased levels of MMP-2 are typically indicative of poor prognostic outcome." (PMID 20525232, 2010). "Previous data from our lab indicated that extracellular hsp90α increases cancer cell invasion by assisting in the activation of MMP-2." (PMID 20553606, 2010). "The selective hyperactivation of p38 MAPK signalling in NSCLC (and other cancer types) has been correlated to malignant transformation via the induction of MMP-2 and CXCR4/SDF-1 chemotaxis axis." (PMID 20226009, 2010). "For example, a recent report indicated that in vitro invasiveness of some cancer cell lines was enhanced via the formation of RGD-dependent complex with MMP-2 and αVβ3 integrin." (PMID 21103065, 2010). "Another study showed that berberine suppresses invasion of cancer cells through different signalling pathways resulting in inhibition of MMP-2 and MMP-9." (PMID 20652055, 2010).
cancer (continued). "Despite overexpression and invasion promoting ability of Lewis (y), and MMP-2 and MMP-9 being separately reported in various types of human cancer, a direct association between Lewis (y) and these two TIMPs has never been described." (PMID 21151448, 2010). "The molecular chaperone hsp90α is secreted from invasive cancer cells and activates MMP-2 to enhance invasiveness, required for the first step in metastasis." (PMID 20553606, 2010). "It is well established that invasiveness and the ability of cancer cells to migrate in vitro and in vivo is mediated by various metalloproteases (including MMP-2 and MMP-9) and urokinase plasminogen system (uPA, uPAR and PAI-1)." (PMID 20404912, 2010). "MMP-2 binds to the surface of cancer cells via the fibronectin type II module repeats of the enzyme." (PMID 19386107, 2009). "Over expression of TIMP-2 can inhibit the activity of MMP-2 and it also inhibits the invasive and metastatic behaviors of cancer cells." (PMID 19636436, 2009). "Cystatin C expression was significantly lower in cancer specimens than in benign tissues (p<0.001) and there was a statistically significant inverse correlation between expression of cystatin C and MMP2 (rs2 = −0.056, p = 0.05)." (PMID 19956729, 2009). "By contrast, it appeared that subjects with positive immunostaining for MMP-2, -8, -9, or -28 in the cancer cells or MMP-9 or ER-β in inflammatory cells would have a better prognosis than other patients." (PMID 18253113, 2008). "A subgroup of MMPs, the gelatinases (MMP-2 and MMP-9), have been particularly implicated in progression, angiogenesis and metastasis of various cancer types." (PMID 18506186, 2008). "With the exception of transformed fibroblasts, re-expression of MMP-2 in cancer cells with impaired function of FAK and subsequent rescue of in vitro cell invasion defects has not been previously studied." (PMID 18349846, 2008). "While not yet undoubtedly proven, our results suggest that this effect is likely mediated by the disturbance in PKC signaling which leads to a reduction of the level of MMP-2, a metalloprotease involved in cancer cell migration during metastasis." (PMID 18294404, 2008). "Here we report, for the first time in cancer cells, direct evidence that MMP-2 is an important player of FAK-mediated cell invasion in HNSCC-derived cells." (PMID 18349846, 2008). "Constitutive expression and activity of MMPs increases the invasiveness of various types of cancer cells, and we have determined characterized the expression of MMP-2, MMP-9 and MMP-14 as well as TIMP-1 and TIMP-2 mRNA in EN-1078D cells, using RT-PCR." (PMID 17894888, 2007). "Confirming the role of MMP-2 and MT1-MMP, radiation enhancement of cancer cell invasion was prevented by an MMP-2 inhibitor and an anti-MT1-MMP antibody." (PMID 17987037, 2007). "The activation intermediate of MMP-2 matures after binding to αvβ3 integrin which is localised at the cancer cell surface and concentrated at the migrating front." (PMID 17987037, 2007). "Localisation of active MMP-2 and αvβ3 integrin at the migration front accelerates cancer cell migration." (PMID 17987037, 2007). "Carcinomas contained significantly higher MMP-2 and MMP-9 levels in antigen as well as activity than adjacent normal tissue." (PMID 16538217, 2006). "Two of the best studied MMP's in angiogenesis and cancer are MMP-2 and MMP-9 (gelatinase-A and -B), which amongst other molecules degrade collagen IV, one of the major components of the basement membrane." (PMID 12189553, 2002).
cancer (continued). "To support the gene expression results, we performed protein expression analysis of the key proteins associated with cancer progression, including MMP2 and MMP9, which are involved in ECM degradation, and N-cadherin, which plays an important role in cancer cell invasion and metastasis." (PMID 41226554, 2025). "Less is known about this pathway to date; however, the presence, interaction, and potency of IGFBPs with this pathway and both PAPPA and MMP2 could shed light on the complex role of this pathway in cancers." (PMID 39854135, 2025). "Additionally, upon analyzing the transcriptional changes that occur in these cells after stimulation, we observed a downregulation of several oncogenes and cancer-associated genes, including IL6, MMP2, and CCND2." (PMID 40043049, 2025). "Invasion and migration of cancer cells may be reduced due to matrix metalloproteinase-2 (MMP-2) downregulation and E-cadherin upregulation by MLX." (PMID 40649764, 2025). "Among these genes, the most overexpressed in platelet-educated cancer cells are those encoding proteins involved in cancer progression and metastasis, including SERPINE1 (358%), MMP2 (297%), MMP10 (214%), TIMP1 (187%), FN1 (166%), TMPRSS4 (146%) and RHOC (102%)." (PMID 40096084, 2025). "However, the upregulation of miR-34a culminated in the increased apoptosis of cancer cells while downregulating MMP-2 and MMP-9 expression, inhibiting invasiveness and migration of cancer cells." (PMID 40575155, 2025). "Xanthohumol (Xn), a phenolic compound rich in hops, wine, and beer, could inhibit cancer progression by blocking MMP-2 and MMP-9 activity." (PMID 40563423, 2025). "The observed anticancer polarization of these cancer-associated fibroblasts in response to treatment may be related to a reduction in CCL2, TNC, MMP9 and MMP-2." (PMID 41009006, 2025). "MMP2 plays a critical role in cancer development by facilitating invasion and angiogenesis, the creation of new blood vessels due to its interactions with cancer and ECs." (PMID 40170079, 2025). "Matrix metalloproteinases-2 and −9 (MMP-2, −9) are key enzymes involved in the degradation of the extracellular matrix, a crucial step for cellular invasion, and are known to play a significant role in the metastasis of various cancers." (PMID 40472740, 2025). "However, in malignant tumors, activated MMP-2 and MMP-9 degrade the matrix, promoting cancer cell infiltration." (PMID 40607416, 2025). "Activated STAT3 is involved in the expression of numerous genes that are crucial for cancer progression, including those involved in migration and invasion (Matrix Metalloproteinase 2 (MMP2), MMP9), epithelial–mesenchymal transition (EMT) properties, and preventing escape and attack." (PMID 40427146, 2025). "In the TME, tumor stromal cells and cancer cells generate MMP2." (PMID 40170079, 2025). "MMP-2 levels increase in proportion to cancer cell viability." (PMID 41304968, 2025). "Therefore, our results suggest that the restoration of E-cadherin through ECN is a potential modulator in controlling cancer cell migration, MMP-2 secretion, and invasion by preventing the EMT process in TGF-β1-stimulated A549 cells." (PMID 40806251, 2025). "Moreover, CAF-derived PDGFC can facilitate the EMT of cancer cells and increase matrix metalloproteinase 2 (MMP2) expression through the PDGFRA-mitogen-activated protein kinase/extracellular signal-regulated kinase (MAPK/ERK) pathway." (PMID 40501228, 2025). "Among MMPs, MMP2 (gelatinase A) has emerged as a key mediator in cancer biology due to its ability to degrade type IV collagen, a major component of the basement membrane, thereby facilitating cancer cell invasion and metastasis." (PMID 38978899, 2024). "Decreased the mobility of MDA-MB-231 cancer cells and the expression of MMP-2 and MMP-9 genes." (PMID 39712006, 2024). "Therefore, targeting MMP2 expression and activity is a potential therapeutic approach to cancer treatment." (PMID 38560573, 2024).
cancer (continued). "Furthermore, cancer progression and metastasis can be accelerated by the impairment of MMPs, especially MMP2 and MMP9, which are a subgroup of Zn-dependent MMPs." (PMID 38732186, 2024). "MMP-2 and MMP-9, in particular, have been associated with cancer metastasis." (PMID 38884093, 2024). "Additionally, we found that MMP2 expression was remarkably increased in cancer tissues, compared to normal adjacent tissue." (PMID 38978899, 2024). "MMP2 and MMP9 are closely associated with the metastasis of malignant tumor cells." (PMID 38430256, 2024). "Among others, the expression of MMP-2 and MMP-9 proteins in CRC tissue as potential biomarker roles is underlined due to their correlation with important clinical data: cancer grade, higher risk of dissemination or disease recurrence, and shorter patient survival." (PMID 39337393, 2024). "Molecularly, RBP4 induced the expression of cancer progression factors MMP2 and MMP9." (PMID 38913193, 2024). "It appears that polyphenols may be valuable options for the chemoprevention and treatment of cancer via the inhibition of MMP-2 and MMP-9 and the suppression of signaling pathways regulating their expression and activity." (PMID 39335164, 2024). "In this regard, quercetin has been shown to impact it by downregulating the expression of matrix metalloproteinases (MMPs) such as MMP9 and MMP2, which play a significant role in the degradation of the extracellular matrix, thereby inhibiting the migration and invasive potential of cancer cells." (PMID 39200268, 2024). "Previous studies suggested that STAT3 activation play a crucial role in the cancer invasion and metastasis by modulating the MMPs expression.Our findings revealed that the expression level of MMP2 and MMP9 was remarkably reduced in MCF-7 cells treated with NAR and DOX." (PMID 38310190, 2024). "Additionally, a significant increase in metalloproteinase MMP2 and MMP9 expression, which are linked to enhanced metastatic potential, further underscored the potential of LMF to influence PC3 cancer cell behaviour." (PMID 39336161, 2024). "DPPA was specifically cleaved from RDCM in response to matrix metalloproteinase-2 (MMP-2) that was overexpressed in the extracellular matrix of cancer cells to block PD-L1, DPPA together with IDO inhibition via 1MT alleviated the immunosuppression of CTLs by TME." (PMID 38628547, 2024). "The role of MMP-2 in the cancer environment has been proposed decades ago." (PMID 39769454, 2024). "Prior reports in cancer demonstrated extracellular Hsp90α and Aha1 can promote MMP-2 activation." (PMID 39776493, 2024). "Furthermore, NF-κB regulates cancer cell invasion by controlling the expression of adhesion molecules such as fibronectin and vitronectin, which influence MMP-2 and MMP-9 activity." (PMID 39684484, 2024). "MMP-2 and MMP-9 are part of the matrix metalloproteinase (MMP) family, known for their ability to break down polymeric collagen and the extracellular matrix (ECM), factors linked to cancer metastasis and angiogenesis." (PMID 38374934, 2024). "As speculated, in two TNBC cell lines, SAMD5 overexpression significantly inhibited cell viability, colony formation, and cell invasion, as well as cancer biomarker levels, including Ki67, MMP2, and MMP9." (PMID 39524172, 2024). "MMP2 and MMP9 lead to polysaccharide deficiency and interrupt the activity of extracellular fibronectin and type IV collagen, which play an important role in the penetration of BM by cancer cells." (PMID 39119085, 2024). "The fine-tuning of cancer cell invasion is dependent on the activated MMP-2." (PMID 39187523, 2024). "FAP and MMP2 had the greatest percentage of patients with marker-present primary cancer tissue and marker-absent adjacent normal tissues (88.5% and 89.8%, respectively), indicating that these markers can specifically label cancer tissue." (PMID 39335130, 2024).